NAA60 (N-alpha-acetyltransferase 60, NatF catalytic subunit)
Description:
N-alpha-acetyltransferase that specifically mediates the acetylation of N-terminal residues of the transmembrane proteins, with a strong preference for N-termini facing the cytosol. Displays N-terminal acetyltransferase activity towards a range of N-terminal sequences including those starting with Met-Lys, Met-Val, Met-Ala and Met-Met. Required for normal chromosomal segregation during anaphase. May also show histone acetyltransferase activity; such results are however unclear in vivo and would require additional experimental evidences.
Synonyms: hNaa60; HAT4; NatF; NAT15; FLJ14154; IBGC9
Tractability: Small molecule: a structure with a bound ligand is known. Antibody: UniProt places it where antibodies can reach, with high confidence.
Target class: Enzyme; Transferase
Gene: Protein-coding gene on chromosome 16 (3,443,649 to 3,486,954, forward strand). Ensembl gene ENSG00000122390.
Subcellular location: Golgi apparatus membrane
Subcellular location (Human Protein Atlas): Actin filaments; Cytosol
Gene Ontology:
Molecular function: histone H4 acetyltransferase activity; protein binding; protein homodimerization activity; protein-N-terminal amino-acid acetyltransferase activity; histone acetyltransferase activity; acyltransferase activity, transferring groups other than amino-acyl groups; protein N-terminal-methionine acetyltransferase activity; protein-lysine-acetyltransferase activity
Biological process: cell population proliferation; N-terminal peptidyl-methionine acetylation; N-terminal protein amino acid acetylation; nucleosome assembly; chromosome segregation
Cellular component: Golgi membrane
Genetic constraint (gnomAD): Loss-of-function variants: 8 observed, 24.04 expected, observed/expected ratio (o/e) 0.33, 90% interval 0.19 to 0.6. The upper end of that interval is the gene's LOEUF score, 0.6, which puts it in group 2 of 6, group 1 being the genes least tolerant of losing a copy. Missense variants: 290 observed, 304.87 expected, observed/expected ratio (o/e) 0.95, 90% interval 0.86 to 1.05. Synonymous variants: 131 observed, 118.96 expected, observed/expected ratio (o/e) 1.1, 90% interval 0.95 to 1.27.
Homologues: Orthologues: rabbit NAA60 (98% identical), guinea pig NAA60 (97% identical), mouse Naa60 (97% identical), pig NAA60 (97% identical), zebrafish naa60 (89% identical), chimpanzee NAA60 (87% identical), dog NAA60 (84% identical), rat Naa60 (83% identical), tropical clawed frog naa60 (81% identical), Drosophila melanogaster Naa60 (48% identical), macaque NAA60 (48% identical), Caenorhabditis elegans F30F8.10 (33% identical).
Diseases named in the same sentence as NAA60 in open-access papers:
NAA60 is named in the same sentence as 7 diseases in open-access papers, as found by Europe PMC text mining. Sharing a sentence is not in itself a finding about the gene and the disease. The quoted sentences say what the papers report.
breast carcinoma (1 paper, 2018). "Our results are consistent with previous breast cancer profiling studies, but also provide unique insights, such as discovery of AFAP1-AS1 and NAA60 as potential TNBC subtype specific genes." (PMID 29458327, 2018).
cancer (2 papers, 2020 to 2022). A tumor composed of atypical neoplastic, often pleomorphic cells that invade other tissues. "Within the DepMap genome-wide CRISPR knockout (KO) screen consisting of 739 cell lines of diverse tissue origin, most NATs were essential to all or to a subset of cancer cells, with the exception of NAA60, NAA80, NAA38, NAA11 and NAA16." (PMID 32942614, 2020).
infection (2 papers, 2016 to 2021). The state of being infected such as from the introduction of a foreign agent such as serum, vaccine, antigenic substance or organism. "Based on this analysis, we found that the level of pSTAT1 in NAA60-depleted cells after 12 h and 24 h of infection was a significant 1.48-fold (P=0.044) and 2.0-fold (P=0.048) higher, respectively, than the control cells." (PMID 35095845, 2021). "In NAA60-depleted cells, the level of pSTAT1 increased even further after 6 h, 12 h and 24 h of infection compared to controls cells." (PMID 35095845, 2021). "Indeed, compared to control, the expression of IFNα mRNA was upregulated in NAA60-depleted cells by a significant 3.2-fold (P=0.0036) and 2.2-fold (P=0.0413) after 3 h and 6 h of infection, respectively." (PMID 35095845, 2021). "Likewise, the IAV-induced expression of IFITM3 polypeptide was further enhanced in NAA60-depleted cells by a significant 1.6-fold (P=0.022) and 1.7-fold (P=0.041) at 12 h and 24 h post-infection, respectively, compared to control cells." (PMID 35095845, 2021). "Consistent with results in NAA60-depleted cells, the expression of IFNα mRNA in NAA60-overexpressing cells was reduced by a significant 51% (P=0.036) and 39.2% (P=0.013) at 3 h and 6 h post-infection, respectively, when compared to control cells." (PMID 35095845, 2021). "Finally, after 24 h of infection, the IAV-induced expression of ISG15 polypeptide in NAA60-depleted cells was further increased by a significant 4.3-fold (P=0.016) compared to control cells." (PMID 35095845, 2021). "The NAA60-depleted cells released 61% and a significant 64% (P=0.038, determined by two-way ANOVA Bonferroni’s test) less infectious viral progeny after 12 h and 24 h of infection, respectively, compared to the control cells." (PMID 35095845, 2021). "Next, NAA60-depleted and control A549 cells or HBECs were infected with influenza virus A/Puerto Rico/8/1934/(H1N1) (hereafter referred to as PR8) or influenza virus A/California/07/2009/(H1N1) (hereafter referred to as CA09) strains at a multiplicity of infection (MOI) of 1.0." (PMID 35095845, 2021).
neurodegenerative disease (1 paper, 2025). A disorder of the central nervous system characterized by gradual and progressive loss of neural tissue and neurologic function. "These discoveries unveil a broader involvement of NAA60 in cellular transport processes and membrane stability, particularly at the Golgi apparatus and position NAA60 as a potential therapeutic target in neurodegenerative diseases." (PMID 39965656, 2025).
NAA60 also shares sentences with these, for which no sentence is quoted: developmental delay (1 paper); primary familial brain calcifications (1); psychosomatic disorders (1).